IL1B (interleukin 1 beta)
Diseases named in the same sentence as IL1B in open-access papers (continued):
Sharing a sentence is not in itself a finding about the gene and the disease.
Autoimmunity (continued). "This potent immune response turns IL-1β into an effective trigger of acute phase responses; however, uncontrolled IL-1β signaling can drive chronic non-resolved inflammation, which is often associated with a wide variety of human pathologies, including autoimmunity and cancer." (PMID 31775389, 2019). "Interestingly, the increased IL-1β production in CGD was linked to a reduction in autophagy that also resulted in defects in phagocyte killing of internalized bacteria and fungi, demonstrating a link between autoimmunity, autophagy, and infectious disease." (PMID 30154791, 2018). "However, high mTOR activities would be expected to phosphorylate the S249 amino acid of DCP2, resulting in increased autophagy-related transcript suppression, which modulates the effect of autophagy on IL-1β and autoimmunity with potential reductions in pathogen clearance." (PMID 30154791, 2018). "The serum levels of pro-inflammatory and immunomodulatory cytokines such as IL-1β, IL-6, IL-8, IL-10, IL-17, and IL-15 were used as secondary study endpoints as they provide a strong evidence of the efficacy of the hMSCs administration inmodulating autoimmunity." (PMID 30254638, 2018). "Therefore, the ability of Tregs to express and release IL-1R2, and possibly also IL-1RA, locally to neutralize IL-1β function could play an important role in dampening inflammation and autoimmunity." (PMID 20066156, 2010). "Canakinumab, a monoclonal antibody targeting IL-1β, has been approved by the FDA for treating autoimmune conditions such as familial cold autoinflammatory syndrome and Muckle–Wells syndrome." (PMID 40564127, 2025). "IL-15 induces the synthesis of certain cytokines that participate in autoimmunity like, for example, TNF-α and IL-1β, by enhancing the maintenance of CD-8 memory T-cell through the inhibition of self-tolerance." (PMID 37206670, 2023). "Our observations illustrate that IL-17A promotes IL-1β production from orbital fibroblasts via the NLRP3 inflammasome in GO, and cytokines subsequently released may induce more inflammation and autoimmunity." (PMID 37109536, 2023). "Other cytokines are decreased, such as IL-1β, IL-6, GM-CSF, and TNF-α, in ASD individuals, which may influence neuronal activity and drive autoimmunity." (PMID 35328471, 2022). "Because inflammation is also associated with islet β-cell communication with immune cells, which influences autoimmunity, we tested the hypothesis that PMI 5011 and DMC2, an isolated compound from the PMI 5011 extract, could modulate sensitivity to IL-1β." (PMID 35625635, 2022). "In addition, we evaluated the impact of IL1β and IL6 largely described as mediators of inflammation and autoimmunity, and GM-CSF, involved in chronic inflammation." (PMID 34774107, 2021). "In autoimmunity, combination therapy with anti-IL-1β and anti-IL-6 antibody has not been tested so far." (PMID 28286780, 2017). "In present work the cellular pathway involved in autoimmunity elicited by mercury salts encompasses endosomal TLR signaling; in turn, this signaling stimulates transcription factor NF-kB and promotes the transcription of the pro-IL-1B and IL-6 genes." (PMID 26064998, 2015). "Yet IL-1β cannot be sufficient for driving autoimmunity as autoreactive T and B cells are not a part of the pathophysiology of autoinflammatory diseases." (PMID 24409181, 2013). "Moreover, TNF-α, IL-1β, and IFN-γ can also activate the generation of pro-inflammatory IL-6 which contributes to the pathogenesis of various diseases, such as inflammation, autoimmunity, and cancers." (PMID 36204610, 2022). "Moreover, IL-1β and TNF-α both can activate the generation of pro-inflammatory IL-6 and then contributes to the pathogenesis of various diseases, such as inflammation, autoimmunity, and malignancies." (PMID 36139256, 2022).
Autoimmunity (continued). "Therefore, inflammasome activity and IL-1β in particular might play a more significant role in insulin sensitivity and beta cell dysfunction (T2D) rather than regulating autoimmunity to beta cells (T1D)." (PMID 24409181, 2013).
myocarditis (99 papers, 2004 to 2025). Myocarditis is a condition that is characterized by inflammation of the heart muscle (myocardium). "Inhibition of TRIM29-PERK signaling pathway can reverse the myocarditis caused by inflammatory cytokines such as IL-6, IL1-β and TNF-α." (PMID 38979420, 2024). "These macrophages secrete IL-1β, which is a cytokine implicated in the transition from acute myocarditis to inflammatory cardiomyopathy." (PMID 37175422, 2023). "During myocarditis, IL-12 signaling increases IL-1β and IL-18, while IL-12 deficiency decreases inflammation and viral replication during myocarditis." (PMID 37175422, 2023). "In mice, TLR4 deficiency has been shown to decrease levels of IL-1β and IL-18, as well as viral replication and myocarditis." (PMID 37175422, 2023). "We also showed that serum sST2 levels are increased by IL-1β and that there is a direct association between cardiac IL-1β levels and sST2 levels in the heart during myocarditis in male BALB/c mice." (PMID 36741845, 2022). "In mice, IL-1β signaling is the main pathogenic event that leads to vasculitis and myocarditis with both processes prevented by anakinra, an IL-1 receptor antagonist." (PMID 33681107, 2021). "In patients with myocarditis, increased amounts of IL-1β and IL-6 correlated with higher levels of pathogenic T helper 17 cells." (PMID 33881711, 2021). "IL-1β, IL-6, and IL-17A responses are elevated in men with myocarditis/cardiomyopathy, and associated with poor recovery from heart failure." (PMID 34445539, 2021). "TNF-α and IL-1β levels are significantly increased in the heart during the innate (6 hours after infection) and adaptive (during acute myocarditis) immune response in susceptible strains of mice (i.e. BALB/c) that develop chronic myocarditis and DCM." (PMID 23675015, 2007). "Moreover, IL-8, IL-1b, and IL-12 can be implemented in the risk stratification of infective myocarditis." (PMID 39766337, 2024). "There is growing evidence that suggests that males have a higher risk of outcomes in the case of myocarditis, despite the fact that they are able to suppress the production of pro-inflammatory cytokines (IL-1β, IL-6 and TNF-α) and increasing the production of anti-inflammatory cytokines." (PMID 37112659, 2023). "The increase in systemic levels of SDF-1, IL-1β and il-6 indicates systemic pro-inflammatory effects induced by ICIs that can directly and indirectly increase the risk of myocarditis, however more detailed studies on the mechanisms of systemic and direct cardiac toxicity will have to be carried out." (PMID 36158826, 2022). "Similarly, in the experimental autoimmune myocarditis model, IL-12Rβ1 signaling and increased IL-1β levels are associated with the development of myocarditis." (PMID 15550215, 2004). "In patients with myocarditis, an unique cytokine signature was observed, consisting high levels of IL-1β, IL-8, IL-12, and IFN-γ." (PMID 40046048, 2025). "Patients with acute myocarditis also have increased serum levels of pro-inflammatory cytokines, including interleukin (IL)−1ɑ, IL-1β, and tumor necrosis factor (TNF)-ɑ." (PMID 40146392, 2025). "Clinical trials investigating the utilisation of IL-1β inhibitors in myocarditis treatment are currently undergoing." (PMID 39920049, 2025). "The in vivo results showed that PE inhibited the increased numbers of WBC, Neu, and increased levels of TNF-α and IL-1β in LPS-induced myocarditis rats." (PMID 40642003, 2025). "Post-infarction myocardial inflammation was characterized by increased Asc and Nlrp3 gene expression and caspase-1, IL-1β, and Nlrc4 protein expression." (PMID 40332346, 2025). "Consistently with the presence of myocardial inflammation, RT-qPCR analysis showed elevated mRNA levels of IL-1β and IL6 shortly after DEP exposure, with a similar trend for TNFα and the macrophage marker EMR1." (PMID 41444986, 2025).
myocarditis (continued). "The Anakinra versus placebo double blind Randomized controlled trial for the treatment of Acute MyocarditIS (ARAMIS) trial was the first randomized study evaluating the inhibition of IL‐1β in AM." (PMID 41098018, 2025). "NLRP3 activation leads to the release of interleukin-1β (IL-1β), tumor necrosis factor-alpha (TNF-α), and interleukin-6 (IL-6), cytokines that are directly implicated in the pathogenesis of myocarditis and other cardiovascular inflammatory disorders." (PMID 40870916, 2025). "In mice, pharmacologic inhibition or genetic deletion of cathepsin B markedly reduced caspase-1 activation and IL-1β release in the heart, thereby attenuating myocarditis severity." (PMID 40832143, 2025). "Therapies targeting interleukin pathways, such as anakinra, an anti-IL-1β, proved to be effective in myocarditis patients." (PMID 38542026, 2024). "IL-1β is rapidly induced in response to T. cruzi and promotes inflammatory activity in acute experimental myocarditis induced by the parasite." (PMID 39119291, 2024). "This is due to the strong association between myocarditis and ACS with inflammatory cytokines, such as IL-1β and IL-6." (PMID 39452475, 2024). "We showed previously that elevated IL-1β levels in the heart directly correlate to elevated cardiac inflammation in males with myocarditis and poor cardiac function by echocardiography." (PMID 39696682, 2024). "Activation of TLR4, NLRP3 and IL-1β in gout are known factors that drive the pathogenesis of myocarditis." (PMID 38464847, 2024). "Clinical response to anakinra treatment during myocarditis was consistent with the IL-1β overproduction." (PMID 38485795, 2024). "Key pro-inflammatory mediators like NFκB, TNF-α, and IL-1β are upregulated in mouse models of viral myocarditis and autoimmune myocarditis and play a crucial role in myocarditis progression." (PMID 39273613, 2024). "The upregulation of NLRP3 expression in ischemic myocardium can promote the expression of caspase‐1 and IL‐1b, and induce the cascade reaction of myocarditis." (PMID 37249295, 2023). "During acute myocarditis, IL-1β elevates the expression of matricellular proteins tenascin C (TN-C) and osteopontin (OPN)." (PMID 37175422, 2023). "Gene ontology analyses identified the upregulation of pathways involved with IL-17, NF-κB, TNF, IL-1β and IL-4 signaling, cell death, and viral life cycle regulators in neutrophils during myocarditis." (PMID 37175422, 2023). "Mitochondrial DNA, if not be eliminated appropriately and timely by autophagy, can trigger IL-1β mediated myocarditis and dilated cardiomyopathy via TLR9 activation." (PMID 35379787, 2022). "Previously we reported that CD11b, TLR4, caspase-1, and IL-1β were increased by testosterone in male mice with myocarditis." (PMID 36741845, 2022). "In adults with acute myocarditis, activation of the inflammasome through the production of pro-inflammatory mediators such IL-1β, IL-18 is widely recognized." (PMID 36018450, 2022). "We measured the levels of the proinflammatory cytokines IL-1β, IL-6, IL-8, and the regulatory cytokine IL-10 in myocarditis and control serum." (PMID 35265721, 2022). "Findings in CVB3 mouse models suggest that the transition of the acute enterovirus myocarditis into a chronic phase depends on a cytokine-driven immune response, in which IL-1β plays a central role." (PMID 34065891, 2021). "In contrast, animals infected with strains that show low virulence showed slight enhancement of NLRP3, caspase-1, IL-1β and discreet myocarditis." (PMID 34336720, 2021). "Correspondent to our observations in CVB3-infected mice, the murine encephalomyocarditis virus-induced myocarditis model also revealed an increased IL-1β expression, which correlated with a pronounced myocardial inflammation, damage, and fibrosis." (PMID 34065891, 2021).
myocarditis (continued). "IL-1β expression is increased in the hearts of mice with viral myocarditis, and its contribution to the pathogenesis of myocarditis is evident by the fact that addition of an IL-1 receptor antagonist reduces CVB-induced cardiac damage in mice." (PMID 34696354, 2021). "Increased IL-1β expression is also a feature of chronic heart inflammation in experimental models of post-myocarditis DCM, induced by infection with encephalomyocarditis virus." (PMID 33833766, 2021). "Other Th1-related pro-inflammatory cytokines like IL-1β, TNF-α, and IL-12 play pathogenic roles in myocarditis as well." (PMID 32269577, 2020). "It is known that IL1β promotes inflammatory activity in acute experimental myocarditis induced by T. cruzi and induces hypertrophy in primary cultures of cardiomyocytes infected by this parasite." (PMID 33193300, 2020). "In this study, utilizing EAM as a disease model, we show that the elevation of pS368Cx43 by IL‐1β via the p38 MAPK signalling pathway contributes to the prolongation of QRS duration in myocarditis." (PMID 29664174, 2018). "Cytokines that are elevated in HIV infections and myocarditis include interleukin (IL)-1β, IL-6, IL-8, tumor necrosis factor (TNF), and platelet-derived growth factor (PDGF)." (PMID 29669571, 2018). "Patients with CCC have high production of inflammatory cytokines such as IFN-γ, TNF-α, IL-1β and nitric oxide (NO) which are involved with myocarditis, fibrosis and myocardial hypertrophy." (PMID 30044791, 2018). "Taken together, in this study, we identified a novel regulatory mechanism that up‐regulation of pS368Cx43 by IL‐1β via p38 MAPK signalling contributes to the prolongation of QRS duration in myocarditis." (PMID 29664174, 2018). "These authors showed severe myocarditis in T. cruzi-infected mice, with intense IL-1β and TNF-α production by macrophages and IFN-γ production by CD4+ and CD8+ T cells." (PMID 30364017, 2018). "Individuals with CCC have high production of inflammatory mediators such as IFN-γ, TNF-α, IL-1β and nitric oxide (NO) which are involved with myocarditis, fibrosis, and myocardial hypertrophy." (PMID 30044791, 2018). "Persistently elevated IL-1β expression was noted in the chronic stage of myocarditis in a mouse model of post-myocarditis DCM induced by the encephalomyocarditis-virus." (PMID 29951067, 2018). "Both IL-1α and IL-1β have been shown to induce myocarditis and aneurysm formation in Lactobacillus casei cell-wall extract mouse model of KD; both being successfully improved with IL-1 blockade treatment such as anakinra." (PMID 28400731, 2017). "On day 7, the mRNA levels of TNF-α, IL-1β and IL-17A were reduced in the group of 0.1 mg/kg nicotine compared to the myocarditis group." (PMID 26507386, 2015). "Innate immune cytokines such as TNF-α, IL-1β, and IL-6 are essential for the development of acute viral-induced myocarditis." (PMID 26507386, 2015). "IL-1β and IL-18 serve a function in the pathogenesis of CVB3-induced myocarditis in susceptible mice." (PMID 24573249, 2014). "Clinical studies have also found increased levels of circulating tumor necrosis factor-α (TNF-α), interleukin (IL)-1β, IL-6 and other pro-inflammatory cytokines in patients with myocarditis." (PMID 23029542, 2012). "TLR4 deficient mice infected with CVB3 develop significantly reduced acute myocarditis that correlates with reduced interleukin (IL)-1β and IL-18 levels in the heart, indicating that TLR4 signaling increases inflammation in the heart." (PMID 23675015, 2007). "Recently, we demonstrated that CB3 infection increases IL-1β and IL-18 levels in the heart during acute myocarditis through IL-12Rβ1 and TLR4 signaling." (PMID 15550215, 2004). "We have found that susceptible BALB/c mice have significantly increased levels of the proinflammatory cytokines TNF-α and IL-1β in the heart during acute CB3 myocarditis." (PMID 15550215, 2004).
myocarditis (continued). "We prove for the first time that PE could protect from myocarditis through P2X7R/NLRP3/IL-1β, PIP2 and MAPK signaling pathways via binding to P2X7R." (PMID 40642003, 2025). "Studies in mouse models of coxsackievirus infection have shown that testosterone promotes TLR4 signalling in myocarditis, which might contribute to increased levels of IL-1β and IL-18, leading to cardiomyocyte apoptosis and contractile dysfunction." (PMID 38681683, 2024). "In addition, in cases of fulminant myocarditis, the release of IL-1β triggers extensive inflammation throughout the myocardium." (PMID 39408157, 2024). "IL-1β is synthesized by adipocytes, macrophages, and neutrophils, and plays a prominent role in conditions such as atherosclerosis, acute myocardial infarction, myocarditis, and chronic or decompensated heart failure." (PMID 39408157, 2024). "The innate cell release of TNFα, IL-1β and IL-6 as well as complement activation are well documented in viral and autoimmune models of myocarditis, especially in males, where they increase acute and chronic myocarditis." (PMID 38464847, 2024). "The patients with myocarditis also showed high levels of IL-1 receptor antagonist (interleukin 1), IL-5, and IL-16 but no proinflammatory cytokines, for example, IL-6, tumor necrosis factor, IL-1B, IL-2 or interferon-γ." (PMID 36498573, 2022). "Moreover, addition of exogenous IL-1β during CVB infection is sufficient to drive myocarditis in mouse strains that were previously resistant." (PMID 34696354, 2021). "The severe autophagy combined with the secretion of IL-1β may be one of the important inducements of the myocarditis in ARV infection." (PMID 31126305, 2019). "They found that the severity of myocarditis, degree of viral replication, and levels of IL-1β/IL-18 expression were significantly reduced in TLR4-deficient mice and that TLR4 as well as IL-12Rβ1 aggravated CVB3 infection and myocarditis but IFN-γ inhibited viral replication." (PMID 29854842, 2018). "Furthermore, IL-1β has been shown to induce myocarditis and coronary aneurysm formation in the Lactobacillus casei cell-wall extract mouse model of KD." (PMID 29721174, 2018). "Thus, TNF-α and IL-1β are involved in the pathogenesis of acute myocarditis and chronic heart disease by increasing inflammation and fibrosis, respectively." (PMID 23675015, 2007). "Furthermore, the severity of acute myocarditis directly correlates with increased levels of IL-1β and IL-18 in the heart." (PMID 15550215, 2004). "Particularly, the four most significantly elevated cytokines in the deficient/insufficient group were IL-1β, IL-8, IL-12, and IFN-γ (all Cohen’s d>0.25), all of which have been shown in our prior study to be specifically associated with NK-cell mediated vaccine-induced myocarditis." (PMID 40046048, 2025). "Likewise, IL-1β mRNA levels positively correlated with cardiac hypertrophy and fibrosis in a post-myocarditis dilated cardiomyopathy mouse model, indicating the potential relationship between IL-1β expression and the progression of viral myocarditis to dilated cardiomyopathy." (PMID 40146392, 2025). "IL-1β was elevated in our cohort of patients, and together with upstream NLRP3 inflammasome activation and associated cytokines may play a role in the pathogenesis of myocarditis." (PMID 37146127, 2023). "Indeed, released damage-associated signals, in addition to elevation of the proinflammatory cytokine IL-1β as seen in patients’ serum, triggered by cardiac injury can induce monocyte/macrophage recruitment, further exacerbating the inflammation in myocarditis and/or resulting in tissue fibrosis." (PMID 37146127, 2023). "Therefore, it is important to decrease myocarditis via decreasing expression of inflammatory cytokines (such as IL-1β and TNF-α) and a master transcriptional factor NF-κB that can modulate many genes responsible for both the innate and adaptive immune response." (PMID 26269254, 2015).